EPO (erythropoietin)
Diseases named in the same sentence as EPO in open-access papers (continued):
Sharing a sentence is not in itself a finding about the gene and the disease.
anemia (continued). "However, as medical insurance in some countries does not approve the use of EPO for the management of anemia from bleeding, it is important to consider if treatment with iron alone would be as effective." (PMID 37624779, 2023). "Erythropoietin levels are actually increased in most patients with anemia of CKD, but this increase may not be adequate for the severity of anemia." (PMID 35905974, 2023). "Because they are effective in activating erythropoietin and regulating iron metabolism, roxadustat (FG-4592), daprodustat (GSK-1278863), vadadustat (AKB-6548), enarodustat (JTZ-951), molidustat (BAY 85–3,934) and desidustat (ZYAN1) are approved for the treatment of anemia in CKD." (PMID 37521459, 2023). "Thus, firstly we decided to analyze and compare kidney function, anemia parameters, serum levels of inflammatory markers, EPO, and sFas between patients with non-dialysis dependent CKD (NDD-CKD) and healthy subjects." (PMID 37390095, 2023). "The role of EPO, iron metabolism and medicine in development of anemia could not be determined in our cohort since the absence of these information." (PMID 36755908, 2023). "Due to the lack of data on markers of iron status (serum iron, ferritin, and transferrin), hepcidin, or erythropoietin, we could not assess the precise mechanisms of anemia in the included study population." (PMID 36008838, 2022). "In this setting, increasing the dose of ruxolitinib to treat splenomegaly and symptoms may not be a viable option because it would further accentuate anemia given the essential role of JAK2-mediated erythropoietin signaling in erythropoiesis." (PMID 35045875, 2022). "Although nephrectomy induced anemia in WT, serum erythropoietin levels did not change." (PMID 35622784, 2022). "However, once anemia develops, the bone marrow exerts its maximum erythropoiesis capacity and does not increase, regardless of anemia aggravation or serum EPO increase." (PMID 35381671, 2022). "In a prospective cohort study, low EPO levels could also predict faster renal function decline independently of established prognostic factors including GFR, albuminuria, and hemoglobin in DN with anemia." (PMID 35453626, 2022). "Nevertheless, around 90% of infants in both groups had anemia during their hospital stay and needed red packed blood cells or erythropoietin therapy but still especially those without therapy or on erythropoietin therapy only had depleted iron stores after discharge." (PMID 35807912, 2022). "It should be noted that the clinically used PHD inhibitors for treatment of anemia in chronic kidney disease appear to be safe, as far as is known, despite the perceived pleiotropic nature of HIF target genes (though, e.g., excessive EPO upregulation is, of course, toxic)." (PMID 35852137, 2022). "Lack of erythropoietin synthesis, inhibition of erythropoietin in bone marrow by cytokine overproduction and bone marrow reduced sensitivity to erythropoietin under inflammatory conditions can explain patient anemia." (PMID 36295889, 2022). "However, there is no coverage for intravenous iron and erythropoietin stimulating agents for anemia care, temporary central lines, dialysis, and transplant." (PMID 35251672, 2022). "Third, iron supplementation in AKI patients with anemia needs to be further studied whether with or without EPO taking into consideration the high rate of functional iron deficiency in this category of patients." (PMID 35279078, 2022). "In patients without CKD, EPO levels rise in response to anemia." (PMID 33498292, 2021). "EPO levels were not significantly increased in newborns with fetal anemia, and this inappropriately blunted response may have contributed to anemia in our study population." (PMID 33995348, 2021).
anemia (continued). "In the HIMALAYAS randomized, open, active-controlled, phase III comparator study (NCT02052310; n = 1043), roxadustat was not worse than alpha erythropoietin in the treatment of anemia in patients who had recently started treatment with hemodialysis, due to terminal renal failure." (PMID 33567688, 2021). "The evidence presented on the role of osteoblasts and osteoclasts activity during EPO‐stimulated erythropoietic response seems likely to further fuel the debate on the relative efficacy and safety of EPO vs HIF‐PHIs for patients who require long‐term treatment for anemia." (PMID 33475252, 2021). "In our study, kidney recipients with B19V infection predominantly presented with unexplained anemia, reticulocytopenia, and no response to erythropoietin therapy, and bone marrow examination (characteristic morphological findings) is also an important diagnostic basis." (PMID 34722340, 2021). "However, in this model, EPO increased 4-fold during the development of CRA, which might be the feedback loop of anemia-induced hypoxia." (PMID 33461597, 2021). "Thus, optimal hemoglobin levels need to be achieved rather than too high levels in order to improve the quality of life of patients with anemia without subjecting them to adverse effects of erythropoietin." (PMID 33628672, 2021). "In addition, anemia and increased FGF23 and EPO can also induce cardiac hypertrophy." (PMID 34362888, 2021). "However, one recipient developed progressive anemia and reticulocytopenia and did not respond well to erythropoietin." (PMID 34722340, 2021). "Finally, other interventions that reduce anaemia such as the use of erythropoietin were not included in our study." (PMID 32620259, 2021). "However, some patients with anemia do not respond well to rhEPO, emphasizing the need for a more biocompatible EPO." (PMID 31977161, 2020). "Therefore, the anemia of CKD is a potent stimulator of FGF23, as improvement of iron utilization via exogenous EPO administration, or endogenous EPO stimulation in mice treated with a HIF‐PHDi, markedly attenuated the increase in circulating iFGF23 concentrations." (PMID 32476270, 2020). "However, no studies evaluating the efficiency of the EPO therapy for anaemia correction in two-stage septic revision arthroplasty are available yet." (PMID 33306020, 2020). "HIF-2α-knockout mice presented anemia, which was not the result of a cell-autonomous defect in erythroid-precursor maturation but of inadequate renal EPO production; moreover, the location of renal HIF-2α-expressing interstitial cells coincides with that of renal EPO-producing cells." (PMID 32708962, 2020). "However, another study reported that 12 infant patients who underwent PD did not have improved erythropoietin-resistant anemia by carnitine supplementation." (PMID 32003308, 2020). "In a model of renal failure-induced anemia, MSC-IGF-1 co-implanted with MSCs genetically engineered to secrete erythropoietin (MSC-EPO) promoted a significant hematocrit elevation when compared to the group which received the MSC-EPO + MSC-null, with a difference of approximately 20% after 98 days." (PMID 32974331, 2020). "Diseased kidneys do not release sufficient amounts of EPO, which may consequently lead to anemia, which is universal in end-stage renal disease." (PMID 32290638, 2020). "Kaplan-Meier analyses showed early diverging curves for anemia vs. non-anemia, whereas curves for patients in various EPO level quartiles started to diverge at about 100 days, with differences consistently increasing during the subsequent entire follow-up period." (PMID 33330669, 2020). "Firstly, taking into account that low oxygen availability triggers EPO production in the kidney, chronic hypoxia itself, due to a subclinical disorder even with no anemia, rather than renal dysfunction, could elevate EPO levels as a physiologic response." (PMID 33330669, 2020).
anemia (continued). "This is particularly relevant in some healthcare systems where CKD patients are unable to afford EPO therapy which might result in anemia requiring blood transfusion, especially while there is a lacking evidence that EPO improves morbidity or mortality in CKD." (PMID 31798530, 2019). "However, large randomized trials to treat anemia in CKD or ESRD patients with EPO supplementation did not evaluate cognitive function." (PMID 31484803, 2019). "This new strategy for treating CKD anemia is already in phase III clinical trials in adults, and the potential advantages of this therapy are that it is orally active (thereby avoiding injections), and patients are exposed to lower circulating levels of erythropoietin." (PMID 29569190, 2019). "However, another study reported no improvement in erythropoietin-resistant anemia by carnitine supplementation in 12 infants who were on PD." (PMID 31689941, 2019). "This was unexpected and, in the light of our experimental data, suggests different effects of slowly rising endogenous erythropoietin levels in response to tumor-related anemia as opposed to relatively large and rapid increases through application of rhEpo in vitro or in vivo." (PMID 30700319, 2019). "In absence of anemia and other hypoxic cases, serum EPO levels in blood are quite low, at around 10 mU mL−1, while, in the presence of anemia or hypoxic stress, serum EPO levels may increase up to 1000-fold, reaching 10,000 mU mL−1." (PMID 31139640, 2019). "In a meta-analysis of 4 randomized controlled trial including men over the age of 50 years, nandrolone was non-inferior to EPO for the treatment of anemia of CKD, especially in developing countries where EPO might be unavailable." (PMID 31798530, 2019). "Measures to deal with the anemia were: expectancy (n = 15); RIBA dose reduction only (n = 12); RIBA dose reduction, erythropoietin treatment, and blood transfusions (n = 4); RIBA dose reduction and blood transfusions (n = 3); and RIBA dose reduction, erythropoietin treatment (n = 1)." (PMID 29536805, 2018). "Interestingly, the mRNA expression levels of EPOR was dramatically suppressed in the bone marrow at early stage of infection, independent of the severity of anemia, EPO expression, and parasitemia levels in both α-TTP knockout and wild type mice." (PMID 30586912, 2018). "Furthermore, in an animal model of inflammation induced functional iron deficiency and anemia (by use of peptidoglycan-polysaccharide), use of a HIF stabilizer (but not EPO injections) improved intestinal iron absorption and corrected anemia." (PMID 29738538, 2018). "The aging process may further affect hematopoiesis by altering the production of hematopoietic ILs and decreasing the production of erythropoietin (EPO) in the kidneys as well as increasing the oxidative damage to erythrocyte membranes, which in turn may lead to anemia of a variety of etiologies." (PMID 29899711, 2018). "In recent findings, CKD anemia might result from a defective hypoxic signaling rather than the lack of EPO-stimulating cells to synthesize EPO." (PMID 29615029, 2018). "Thus, anemia of CKD may be treated with additional therapeutic avenues beyond iron and EPO supplementation." (PMID 29738538, 2018). "In this study, average hemoglobin levels in patients with anemia were 36.0 ± 8.9 g/L for the most affected cases, who did not receive transfusion; anemia was corrected by auxiliary methods such as iron supplementation and erythropoietin administration." (PMID 29349068, 2017). "None of the patients had received erythropoietin or blood transfusion for the treatment of anaemia." (PMID 28229219, 2017). "Besides the lack of EPO, shortened erythrocyte lifespan has been accepted as one of the contributory factors to anemia in patient with ESRD." (PMID 28158274, 2017).
anemia (continued). "This may be due to the fact that our patients, overall, showed mild anaemia; thus, they may not have been exposed to a hypoxic stimulus, substantial enough to significantly increase EPO levels." (PMID 28191453, 2017). "Moreover, its predictive value was deemed significant independently from hemoglobin levels and other several important predictive factors, regardless of the presence of established anemia or the history of erythropoietin treatment or RBC transfusion." (PMID 29062112, 2017). "Since the dosage of EPO in our study was very close to the current clinical dosage in neonate anemia, and did not induce severe elevation of Ht, we believe that the dosage of EPO used here might also safely be used clinically in obese or diabetic children." (PMID 28288167, 2017). "In the current study, the prevalence of anemia was >90% in patients with stage 5 CKD; this may be attributed to the decreased production of endogenous EPO due to a decrease in eGFR, as well as metabolic disturbances such as uremic toxins and electrolyte and acid-base imbalances." (PMID 27310973, 2016). "Overall, KIAA0101 appears to be a key promoter of RCC malignancy induced by EPO, which provide mechanistic insights into KIAA0101 functions, and pave the road to develop new therapeutics for treatment of cancer-related and chemotherapy-induced anemia in patients with RCC." (PMID 26575329, 2016). "As the destruction of red blood cells and the inhibition of erythropoiesis are known to trigger the production of EPO in response to hypoxia, it is conceivable that increased EPO levels observed in patients from Uganda were attributable to severe anemia and not to CM." (PMID 27441662, 2016). "Third, we did not examine other factors related to anemia, most notably EPO." (PMID 27918575, 2016). "Still, EPO administration fails to reduce anemia in 10% of patients." (PMID 26445018, 2015). "It is possible that this effect might be a result of the modulatory action of GH on the production of erythropoietin (EPO), as increased concentrations of GH augment the levels of EPO in GHD patients with developed anemia, possibly due to increased hepatic synthesis of EPO." (PMID 25920498, 2015). "This neokidney may secrete host cat’s EPO (without causing an immune response) and thereby improve the CKD-induced anemia in the host cat." (PMID 25671605, 2015). "Recent evidences suggest that CKD anemia might be due to a defective hypoxic signaling rather than an inability of the EPO-producing cells to synthesize EPO." (PMID 26712750, 2015). "In addition to the practice of EPO in the treatment of anemia and renal diseases, emerging evidence suggests that EPO has other beneficial effects on nonerythroid tissues." (PMID 26101463, 2015). "Third, due to the lack of data on markers of iron status (serum iron, ferritin, and transferrin), hepcidin, or erythropoietin, we could not assess the mechanisms of anemia in our study population." (PMID 24878740, 2014). "Indeed anemia was the most common SAE and the most frequent reason for treatment discontinuation, ultimately requiring blood transfusions in 10% of the patients and Erythropoietin support in nearly 20% of enrolled patients." (PMID 24760000, 2014). "Moreover, although RbvDR are considered by the experts to be the best strategy to manage severe anemia during TVR, in some cases severe anemia is so quick to develop that erythropoietin and blood transfusion are necessary to improve the patients quality of life while continuing PR+TVR treatment." (PMID 24760000, 2014). "Erythropoietin (EPO) is a pleiotropic cytokine that was initially identified as an essential regulator of red blood cell production through the homodimer EPO receptor (EPOR2) expressed on the surface of hematopoietic progenitor cells and is widely applied to treat the anemia of various origins." (PMID 24603865, 2014). "Patients without anemia, but with high serum EPO (sEPO) levels are rare among HD patients." (PMID 25295086, 2014).
anemia (continued). "First, we did not account for the possible correction of anemia before primary radiotherapy; blood transfusion and administration of erythropoietin in cancer patients may help improve anemia and patient survival." (PMID 25085112, 2014). "While the question remains about how a low level of EpoR can provide a direct EPO response, various responses to EPO observed in animal and cell models of ischemic stress, injury or metabolism in non-hematopoietic tissues suggest therapeutic benefit for EPO beyond anemia." (PMID 24918289, 2014). "Unlike EPO, EpoR expression is not affected by hypoxia or anemia." (PMID 23847596, 2013). "However, EPO is currently being used successfully to treat anemia without apparent toxicity as an obstacle for its use." (PMID 24019878, 2013). "The inflammatory response created by a subclinical or silent infection may lead to decreased responsiveness of bone marrow to erythropoietin mediated by inflammatory cytokines, specifically interleukin 1 (IL-1) and tumor necrosis factor alpha (TNF-α) and thus anemia." (PMID 24369448, 2013). "The mild anemia observed may be the result of chronic inflammation which can depress erythropoietin and hemoglobin synthesis, but does not appear to exacerbate severe IDA." (PMID 23547888, 2013). "None of the 15 patients with anemia at 1 year post-transplant received erythropoietin." (PMID 24237955, 2013). "Of note, none of these trials allowed the use of erythropoietin therapy to treat anemia." (PMID 24118976, 2013). "Indeed, cancer-related and chemotherapy-induced anemia that represents a further negative variable in the quality of life for many cancer patients prompted clinicians to use EPO and EPO derivatives in several clinical trials." (PMID 23052842, 2013). "While one might speculate that this is due to amelioration of anemia with EPO treatment, reduced interferon (IFN)-γ and TNF-α mRNA levels in the brain and diminished neuronal apoptosis imply an anti-inflammatory role of EPO treatment in cerebral malaria." (PMID 22094132, 2012). "This suggests that renal dysfunction plays a role in the blunted EPO production in anemic patients with CHF, resulting in increased EPO levels but not as expected for the degree of anemia, suggesting that in CHF there is both blunted EPO production and resistance to EPO." (PMID 22536520, 2012). "A negative feedback effect on erythropoietin production in subjects as a result of the anaemia could be responsible for the thrombocytosis." (PMID 22849350, 2012). "Expression of EPO from KiSAS cells is equivalent to that observed from primary renal cell populations currently under development for cell therapy of anemias secondary to CKD, suggesting that kidney sourced adipose may represent an alternate cell source for cellular vectors for EPO delivery." (PMID 21957910, 2011). "In this study not using of EPO before transplantation was a major risk factor for PTA (p < 0.0001), so patients may still have significant anaemia at time of transplantation." (PMID 21827693, 2011). "However, according to Spivak, the suppression of erythropoietin production in inflammatory conditions such as cancers, cannot be the solely explanation for anemia since the level of plasma erythropoietin is not affected in a sufficient amount." (PMID 20204172, 2009). "However, in a current randomized trial correction of anemia with erythropoietin did not result in survival benefit." (PMID 17150114, 2006). "However, in a recent study among 12-month old HIV-infected Malawian infants, EPO response to anemia was not different than the response in uninfected infants." (PMID 16390553, 2006). "However, by 6 months of age, the EPO response to anemia was not different than that observed among uninfected infants." (PMID 16390553, 2006).